ANP32A (acidic nuclear phosphoprotein 32 family member A)
Description:
Multifunctional protein that is involved in the regulation of many processes including tumor suppression, apoptosis, cell cycle progression or transcription. Promotes apoptosis by favouring the activation of caspase-9/CASP9 and allowing apoptosome formation. In addition, plays a role in the modulation of histone acetylation and transcription as part of the INHAT (inhibitor of histone acetyltransferases) complex. Inhibits the histone-acetyltransferase activity of EP300/CREBBP (CREB-binding protein) and EP300/CREBBP-associated factor by histone masking. Preferentially binds to unmodified histone H3 and sterically inhibiting its acetylation and phosphorylation leading to cell growth inhibition. Participates in other biochemical processes such as regulation of mRNA nuclear-to-cytoplasmic translocation and stability by its association with ELAVL1 (Hu-antigen R). Plays a role in E4F1-mediated transcriptional repression as well as inhibition of protein phosphatase 2A. (Microbial infection) Plays an essential role in influenza A, B and C viral genome replication. Mechanistically, mediates the assembly of the viral replicase asymmetric dimers composed of PB1, PB2 and PA via its N-terminal region. Also plays an essential role in foamy virus mRNA export from the nucleus.
Synonyms: pp32; LANP; PHAPI; C15orf1; MAPM; PHAP1; I1PP2A; mapmodulin; HPPCn
Tractability: PROTAC: ubiquitination databases record sites on it; its protein half-life has been measured.
Gene: Protein-coding gene on chromosome 15 (68,778,534 to 68,820,924, reverse strand). Ensembl gene ENSG00000140350.
Subcellular location: Nucleus; Cytoplasm; Endoplasmic reticulum
Subcellular location (Human Protein Atlas): Nucleoplasm; Centrosome; Cytosol
Pathways (Reactome):
Metabolism of RNA: HuR (ELAVL1) binds and stabilizes mRNA
Gene Ontology:
Molecular function: protein binding; RNA binding; histone binding
Biological process: nucleocytoplasmic transport; base-excision repair; granzyme-mediated apoptotic signaling pathway; intracellular signal transduction; regulation of apoptotic process; regulation of transferase activity
Cellular component: cytoplasm; cytosol; endoplasmic reticulum; nucleoplasm; nucleus; perinuclear region of cytoplasm; chromatin; transcription regulator complex
Genetic constraint (gnomAD): Loss-of-function variants: 1 observed, 33.1 expected, observed/expected ratio (o/e) 0.0302, 90% interval 0.01 to 0.14. The upper end of that interval is the gene's LOEUF score, 0.14, which puts it in group 1 of 6, group 1 being the genes least tolerant of losing a copy. Missense variants: 155 observed, 315.32 expected, observed/expected ratio (o/e) 0.49, 90% interval 0.43 to 0.56. Synonymous variants: 115 observed, 127.01 expected, observed/expected ratio (o/e) 0.91, 90% interval 0.78 to 1.06.
Homologues: Orthologues: chimpanzee ANP32A (100% identical), dog ANP32A (95% identical), macaque ANP32A (94% identical), mouse Anp32a (89% identical), rat Anp32a (85% identical), zebrafish anp32a (85% identical), tropical clawed frog anp32a (82% identical), Drosophila melanogaster Mapmodulin (51% identical), Caenorhabditis elegans F33H2.3 (36% identical), Caenorhabditis elegans T19H12.2 (32% identical). Paralogues in human: ANP32B (71% identical), ANP32E (65% identical), ANP32D (47% identical).
Diseases named in the same sentence as ANP32A in open-access papers:
ANP32A is named in the same sentence as 45 diseases in open-access papers, as found by Europe PMC text mining. Sharing a sentence is not in itself a finding about the gene and the disease. The quoted sentences say what the papers report.
Alzheimer disease (8 papers, 2011 to 2023). A progressive, neurodegenerative disease characterized by loss of function and death of nerve cells in several areas of the brain leading to loss of cognitive function such as memory and language. "Due to its diverse biological activities, dysfunction of ANP32A was already associated with other neurodegenerative-related diseases such as Alzheimer’s disease or Spinocerebellar ataxia and was also discussed as a potential therapeutic target." (PMID 37509196, 2023). "Upregulated ANP32a also increases Tau phosphorylation, impairing the microtubule network and neurite outgrowth in Alzheimer’s disease." (PMID 36555564, 2022). "In the CNS, ANP32A contributes to the survival and differentiation of neurons, as well as synaptic plasticity and memory in aged mice or tau transgenic mice used as a model of Alzheimer’s disease." (PMID 33823794, 2021). "In addition to ANP32A, proteins which have been reported to participate in Alzheimer's disease and related neurodegeneration were present in only the mTau exosomes, and not in control exosomes." (PMID 32295833, 2020). "The level of ANP32A (I1PP2A) is increased in Alzheimer's disease (AD) and may be involved in regulatory mechanism of affecting Tau phosphorylation and impairing the microtubule network and neurite outgrowth." (PMID 25866766, 2015). "Interestingly, the selective knockdown or down-regulation of ANP32A ameliorated the cognitive deficits as well as the synaptic plasticity in different experimental animal models for Alzheimer’s disease (AD) and was discussed as a potential molecular marker for neuroprotection." (PMID 37509196, 2023). "There are suggestions that Anp32a may play important roles in the brain as the level of Anp32a is increased in Alzheimer’s disease and may be involved in the regulatory mechanism of affecting Tau phosphorylation and impairing the microtubule network and neurite outgrowth." (PMID 28610618, 2017).
influenza (8 papers, 2015 to 2025). An acute viral infection of the respiratory tract, occurring in isolated cases, in epidemics, or in pandemics; it is caused by serologically different strains of viruses (influenzaviruses) designated A, B, and C, has a 3-day incubation period, and usually lasts for 3 to 10 days. "In humans, both ANP32A and ANP32B support influenza polymerase activity, whereas in chickens, only ANP32A is required." (PMID 41308154, 2025). "ANP32A is the only ANP32 family member that efficiently supports influenza polymerase in birds, while in humans and most other mammalian influenza hosts ANP32A and ANP32B can both support polymerase activity to varying levels." (PMID 37074204, 2023). "Our work contributes to understanding the mechanism by which ANP32A/B regulates influenza virus replication and provides a new target for developing new anti-influenza drugs." (PMID 35044222, 2022). "In this study, we show that swANP32A, as well as other ANP32A from different species including human, dog, and horse, are universally capable of supporting influenza viral polymerases from humans, pigs, dogs, and horses." (PMID 32084248, 2020). "To conclude, we hypothesize that the superior proviral function of swine ANP32A for supporting influenza replication may enable swine to act as intermediary hosts for avian influenza viruses and also affect the way the viruses evolve as they pass from birds through swine and into humans." (PMID 32269123, 2020). "We next tested the ability of ANP32A and ANP32B proteins from different mammalian species relevant to influenza ecology to support influenza A polymerase activity." (PMID 37074204, 2023). "ANP32A and ANP32B have been previously identified binding with viral polymerase and promoting human influenza viral vRNA synthesis." (PMID 30996088, 2019). "We observed similar results from the reconstitution of ANP32B or both ANP32A and ANP32B, indicating that huANP32A&B are key factors in triggering the replication of the human influenza viral genome." (PMID 30996088, 2019). "Human ANP32A and ANP32B contribute equally to support human influenza viral RNA replication." (PMID 30996088, 2019).
breast carcinoma (6 papers, 2014 to 2023). "It has been long recognized that ANP32A function as a tumor suppressor in several human cancers, including pancreatic and breast cancer." (PMID 26918356, 2016). "Our analysis confirmed the down-regulation of RPL13, and newly identified down-regulation of HDAC1, ANP32A, and the up-regulation of SNX2 as having the worst prognostic effects in normal-subtype breast cancer tumors (panels C4–C7)." (PMID 35971177, 2022). "Interestingly, ANP32A and STK24 were observed to be significantly up-regulated with PRG treatment in nPR(+) T47D cells (panel A1), preliminarily classifying these genes as PRG-inducible biomarkers in Luminal-A breast cancer cells." (PMID 35971177, 2022). "These two specific shRNAs could effectively knockdown ANP32B but not its closely related ANP32A expression in these breast cancer cell lines." (PMID 26844697, 2016).
glioma (5 papers, 2018 to 2023). A benign or malignant brain and spinal cord tumor that arises from glial cells (astrocytes, oligodendrocytes, ependymal cells). "ANP32a expression is also upregulated in glioma patients, promoting the proliferation of glioma cells through the Akt/p27/stathmin pathway." (PMID 36555564, 2022). "In hepatocellular carcinoma and glioma, it was discovered that ANP32a promotes cellular proliferation." (PMID 36555564, 2022). "However, certain studies have reported that ANP32A contributes to the development of cancers, such as leukemia, colorectal cancer, and glioma." (PMID 35280441, 2022). "High ANP32A expression indicates poor prognosis of acute myeloid leukemia and glioma." (PMID 35280441, 2022). "For example, ANP32a could be an oncogene that promotes glioma cell proliferation by regulating the Akt/p27/stathmin pathway." (PMID 36555564, 2022). "ANP32A indicates a poor prognosis in HCC, acute myeloid leukemia, and glioma." (PMID 35280441, 2022).
pancreatic cancer (5 papers, 2010 to 2022). "ANP32a has been proposed as an inhibitor of tumor growth in pancreatic cancer, prostate cancer and lung cancer." (PMID 36555564, 2022). "Earlier studies suggested a role for ANP32A expression as a prognostic biomarker in pancreatic cancer." (PMID 26918356, 2016). "The expression of protein phosphatase 32 (PP32, ANP32A) is low in poorly differentiated pancreatic cancers and is linked to the levels of HuR (ELAV1), a predictive marker for gemcitabine response." (PMID 21152064, 2010). "It has been reported that ANP32A can inhibit the progression of pancreatic cancer and lung cancer." (PMID 35280441, 2022). "Most of the studies have found that, ANP32A function as a tumor suppressor protein, surprisingly increased expression was found in hepatocellular carcinoma, colorectal cancer, pancreatic tumor and liver cancer." (PMID 26918356, 2016).
lymph node metastasis (4 papers, 2010 to 2020). "Overexpression of ANP32A was associated with lymph node metastasis, which predicted poor survival in oral squamous cell carcinoma (OSCC) patients." (PMID 33329703, 2020). "Because ANP32A expression was associated with lymph node metastasis and tumor differentiation, we further evaluated the joint effect of ANP32A expression and the two pathological factors on mortality." (PMID 26918356, 2016). "In this present study, we found that lymph node metastasis (N2/N3) patients with high ANP32A expression had a worst prognosis at a 10 year follow up." (PMID 26918356, 2016). "Patients with a high level of ANP32A expression defined by Allred and IRS scoring systems were respectively found to have a 2.2-fold (95% CI, 1.2-4.0) and 2.0-fold (95% CI, 1.1-3.6) risk of contracting N2/N3 of lymph node metastasis." (PMID 26918356, 2016).
oral squamous cell carcinoma (4 papers, 2016 to 2020). "In this present study we determined the expression pattern of ANP32A in oral squamous cell carcinoma and its correlation with clinicopathological features, including the overall survival of OSCC patients." (PMID 26918356, 2016).
avian influenza (3 papers, 2019 to 2023). Infection of domestic and wild fowl and other birds with influenza A virus. "Interestingly, chicken ANP32A (chANP32A) has been reported to specifically promote avian influenza replication due to the 33-amino-acid insert." (PMID 30996088, 2019). "For efficient replication in mammalian cells, the avian influenza RNA-dependent RNA polymerase must adapt to use human orthologues of the host factor ANP32, which lack a 33-amino-acid insertion relative to avian ANP32A." (PMID 36645303, 2023).
colorectal cancer (3 papers, 2018 to 2023). A primary or metastatic malignant neoplasm that affects the colon or rectum. "Our previous study demonstrated that high expression of ANP32A was found in the tumor tissues of colorectal cancer (CRC) patients and was positively associated with tumor grading." (PMID 37781083, 2023).
leukemia (3 papers, 2011 to 2024). A malignant (clonal) hematologic disorder, involving hematopoietic stem cells and characterized by the presence of primitive or atypical myeloid or lymphoid cells in the bone marrow and the blood. "Consequently, Nucant-mediated occurrence of cell death in leukemia cells might be associated, at least in part, with the functioning of ANP32A and SET." (PMID 21812966, 2011). "While there have been no direct reports on the regulation of histone modification by ANP32B, its counterpart ANP32A, another member of the ANP32 protein family, has been implicated in the regulation of histone acetylation in leukemia pathogenesis." (PMID 38383388, 2024). "The role of ANP32A in the pathogenesis of leukemia has been substantiated by studies." (PMID 38383388, 2024). "ANP32A, a member of the ANP32 family, has been identified as a contributor to leukemia development by modulating acetyl-H3 levels on crucial pathways such as lipid metabolism." (PMID 38383388, 2024).
cardiac hypertrophy (2 papers, 2023 to 2025). "ANP32a-deficient mice have activated Wnt signaling and develop cardiac hypertrophy." (PMID 40709334, 2025).
cognitive decline (2 papers, 2017 to 2023). "Accordingly, the ANP32A-induced hypoacetylation of histones as important epigenetic regulation seems to be responsible for the cognitive decline in AD in vivo." (PMID 37509196, 2023).
non-small cell lung carcinoma (2 papers, 2016 to 2025). A group of at least three distinct histological types of lung cancer, including non-small cell squamous cell carcinoma, adenocarcinoma, and large cell carcinoma. "However, it has been reported that ANP32A overexpression was not significantly correlated with pathological parameter in cancers like pancreatic and non-small cell lung cancer." (PMID 26918356, 2016).
oral cancer (2 papers, 2016 to 2017). "Abrogating ANP32A expression in highly invasive oral cancer cell decreases its metastasis and invasive levels." (PMID 26918356, 2016). "Our in vitro results further showed that, knockdown of ANP32A in oral cancer cells reduced its invasive and metastatic ability." (PMID 26918356, 2016). "ANP32A was found to over express to varying degrees in oral cancer cells." (PMID 26918356, 2016). "We further investigated whether ANP32A over expression increased the invasive potential of oral carcinoma cell lines." (PMID 26918356, 2016).
glaucoma (1 paper, 2023). Increased pressure in the eyeball due to obstruction of the outflow of aqueous humor. "In conclusion, the synthetic CDR1 peptide provides a great translational potential for the treatment of glaucoma in the future by eliciting its neuroprotective mechanism via specific interaction with ANP32A’s N terminal LRR domain." (PMID 37509196, 2023). "All these findings emphasize the great potential of ANP32A as an auspicious drug target molecule in glaucoma therapy as well as for the treatment of other age-related neurodegenerative diseases." (PMID 37509196, 2023). "However, further studies are needed to explore the biological function of ANP32A as a potential drug target in glaucoma therapy and to assess its medical application profile for clinical interventions in the future." (PMID 37509196, 2023). "However, the functional role of ANP32A is largely unexplored in glaucoma so far and might serve as attractive molecular target structure for RGC neuroprotection in glaucoma research." (PMID 37509196, 2023).
intraductal papillary mucinous neoplasms (1 paper, 2016). "ANP32A was absent or reduced in poorly differentiated tumors and in intraductal papillary mucinous neoplasms with moderate dysplasia." (PMID 26918356, 2016).
ovarian carcinoma (1 paper, 2017). A malignant neoplasm originating from the surface ovarian epithelium. "The role of ANP32A in various cancers, including prostate, colorectal, and ovarian cancer, has been described." (PMID 28486557, 2017).
spinocerebellar ataxia type 1 (1 paper, 2022). Spinocerebellar ataxia type 1 (SCA1) is a subtype of type I autosomal dominant cerebellar ataxia (ADCA type I) characterized by dysarthria, writing difficulties, limb ataxia, and commonly nystagmus and saccadic abnormalities. "ANP32a reduction may contribute to abnormal neuritic morphology in the dominantly inherited neurodegenerative disorder, spinocerebellar ataxia type 1." (PMID 36555564, 2022). "ANP32a is also a positive factor in the Spinocerebellar ataxia type 1 (SCA1) transgenic mouse model." (PMID 36555564, 2022).